RIPK3 (receptor interacting serine/threonine kinase 3)
Diseases named in the same sentence as RIPK3 in open-access papers (continued):
Sharing a sentence is not in itself a finding about the gene and the disease.
melanoma (continued). "Although the exact mechanism by which the two classes of inhibitors interact to induce necrosis of BRAFV600E melanoma cells remains to be defined, a number of factors including RIPK1, RIPK3, and generation of ROS do not appear to have a major role." (PMID 23744355, 2013). "The CV extract has been also reported to induce RIPK1/RIPK3/MLKL-mediated necroptosis in non-pigmented melanoma cells and depigmented (with suppressed melanogenesis) melanoma cells, since co-treatment of the cells with necroptosis inhibitors abrogated the CV-induced cell death." (PMID 36902290, 2023).
colorectal cancer (38 papers, 2016 to 2025). A primary or metastatic malignant neoplasm that affects the colon or rectum. "Studies have also revealed the tumor-suppressing effects of RIPK3, especially in colorectal cancer, where low RIPK3 expression is linked to reduced disease-free survival and overall survival." (PMID 38994937, 2024). "Recently, in a pre-clinical model of colorectal cancer there has emerged a circuit based on down-regulation of receptor-interacting serine/threonine-protein kinase 3 (RIPK3) in MDSCs linked to the production of PGE2." (PMID 31130949, 2019). "RIPK3 could suppress CXCL1-induced immunity for promoting colitis-associated colorectal cancer, and the release of CXCL5 could aggravate the migration and invasion of pancreatic cancer." (PMID 36611858, 2022). "In addition, several studies have shown that RIPK3 knockout mice have a higher risk of colorectal cancer and produce more pro-inflammatory or tumor-promoting factors." (PMID 35965497, 2022). "Furthermore, RIPK3 knockout mice were reportedly at a higher risk of developing colitis-associated colorectal cancer and producing a higher number of pro-inflammatory or tumor-promoting factors." (PMID 31122251, 2019). "The inhibitory effect of necroptotic apoptotic factor receptor–interacting protein kinase 3 (RIPK3) in colorectal cancer has been reported, and decreased RIPK3 expression significantly reduces overall survival (OS)." (PMID 39663596, 2024). "Resibufogenin, a bioactive compound extracted from toad venom, has been reported to suppress the growth and metastasis of colorectal cancer by activating RIPK3 necroptosis." (PMID 39061173, 2024). "Chloroquine increases the expression of endogenous RIPK3 in colorectal cancer cell lines, with necroptosis being the mechanism." (PMID 39620145, 2024). "Relevant research results show that low RIPK3 content will directly reduce the survival rate of ovarian cancer, colorectal cancer and breast cancer." (PMID 37878133, 2023). "In human tumor samples, researchers found that the content of RIPK3 was reduced, such as acute myeloid leukemia, chronic lymphocytic leukemia, as well as common colorectal cancer and breast cancer in clinical practice." (PMID 37878133, 2023). "The RIPK1 inhibitor Necrostain-1 inhibits colorectal cancer cell necroptosis via the RIPK1/RIPK3/MLKL signaling pathway." (PMID 36604411, 2023). "The recent study found that TRAF6 inhibits necroptosis in colorectal cancer cells via the RIPK1/RIPK3/MLKL signaling pathway." (PMID 36604411, 2023). "RIPK3 is downregulated in a variety of malignancies, including breast cancer, colorectal cancer, and melanoma." (PMID 36186479, 2022). "Downregulation of RIPK3 promotes lymphatic metastasis in colorectal cancer and results in a poor pathological stage and prognosis." (PMID 36611858, 2022). "More importantly, overall survival was significantly higher in patients with high RIPK3 expression than in patients with reduced RIPK3 expression in colorectal cancer." (PMID 33996591, 2021). "A decreased RIPK3 expression has also been reported in samples from human patients with cancer, such as breast cancer, colorectal cancer, acute myeloid leukemia (AML) and melanoma." (PMID 31122251, 2019). "Resibufogenin inhibits colorectal cancer cell line growth by increasing RIPK3 expression." (PMID 39620145, 2024). "High expression of RIPK3 significantly inhibited the expansion of colorectal cancer cells in vitro." (PMID 35965497, 2022). "Furthermore, decreased RIPK3 expression has been observed to independently predict lower overall survival in colorectal cancer and breast cancer." (PMID 36186479, 2022). "Similarly, RIPK3 was decreased in colorectal cancer and acute myeloid leukemia and the downregulation of RIPK3 hampered the survival of patients." (PMID 35756487, 2022). "RIPK3 plays an important role in the regulation of necroptosis in breast and colorectal cancers." (PMID 36338998, 2022).
colorectal cancer (continued). "Likewise, some reports point out that genomic methylation and/or hypoxia can play an oncogenic role in colorectal cancer cell lines via silencing of RIPK3 expression." (PMID 36361505, 2022). "Furthermore, downregulated RIPK1 and RIPK3 expression has been documented in colorectal cancer tissues versus normal tissues, and thus, their reduced expressions impair cancer cells’ responses to necroptosis stimulation." (PMID 36361505, 2022). "Here we provide evidence that RIPK3 has a critical role in suppressing colorectal cancer (CRC)." (PMID 27344176, 2016). "In addition, the tumor-suppressing effects of RIPK3 have been documented in colorectal cancer." (PMID 31122251, 2019). "Decreased expression of RIPK3 was connected with poor prognosis for women with breast cancer, and decreased OS and PFS in patients with colorectal cancer, as well as accelerated leukogenesis in patients with AML." (PMID 40508046, 2025). "Transient and stable overexpression of TRAF6 in colorectal cancer cells significantly decreased the protein levels of RIPK1 and p-RIPK1 as well as downstream p-RIPK3 and p-MLKL produce inhibition." (PMID 36604411, 2023). "Knockdown of TRAF6 in colorectal cancer cells significantly up-regulated the protein levels of RIPK1 and p-RIPK1 and downstream p-RIPK3 and p-MLKL." (PMID 36604411, 2023). "Comparison of their expression in HUVEC and HT-29, a human colorectal carcinoma cell line, revealed that RIPK1 and MLKL were expressed in HUVEC and HT29, while RIPK3 was normally expressed in HT29 but at an extremely low level in HUVEC." (PMID 32332696, 2020). "The recent study demonstrated that TRAF6 promotes colorectal cell progression by inhibiting the RIPK1/RIPK3/MLKL necroptosis signaling pathway, which may provide a new therapeutic target for colorectal cancer." (PMID 36604411, 2023). "Besides the ability to inhibit cytotoxic T cell responses, PGE2 suppressed RIPK3 expression in MDSC and colorectal cancer cells and induced NF-κB/COX-2 and expression of arginase 1 (ARG-1)." (PMID 32931721, 2020). "According to related studies, the expression of RIPK3 is absent or significantly reduced in many cancer cell lines; for example, compared with normal colorectal mucosal cells, the expression of RIPK3 is significantly reduced in colorectal cancer." (PMID 35965497, 2022).
breast cancer (36 papers, 2016 to 2026). A primary or metastatic malignant neoplasm involving the breast. "To investigate this possibility, we measured the content of RIPK3 mRNA in the breast cancer cells that had been exposed to the tested DS variants for 3 h using real time qPCR." (PMID 39062543, 2024). "The expression of these genes was analyzed in the breast cancer cells that had been exposed to the variants for three hours because, after such an incubation period, the effects of these glycans on both the RIPK3 upregulation and MLKL activation were observed in our previous studies." (PMID 41148796, 2025). "In addition, low RIPK3 expression is associated with a worse prognosis in patients with breast cancer due to genomic methylation." (PMID 36361505, 2022). "The RIPK3 mRNA is typically expressed at lower levels in breast cancer cells when compared to normal cells, as per the TCGA database, and can be silenced by DNA methylation." (PMID 41596270, 2026). "But, the reproducibility of many studies around this topic seems to be poor, and as for other entities like colon cancer or breast cancer, contrasting data exist on the role of RIPK3 protein." (PMID 39858052, 2025). "This necrosis is often accompanied by a decrease in the expression of key necrosis-related molecules, such as RIPK3, in breast cancer cell lines (e.g., MDA-MB-231 and MCF-7)." (PMID 38001342, 2024). "Despite the decrease in RIPK3 expression, the addition of morin with Dox still increased necrotic cell death in the breast cancer cells." (PMID 37242455, 2023). "Paradoxically, high expression of RIPK3 leads to productive proliferation and necrotic vulnerability in recurrent breast cancer." (PMID 37993258, 2023). "RIPK3 is thought to be a carcinogenic factor in various cancers, such as breast cancer, intestinal and colon cancer, and lung cancer." (PMID 35907206, 2022). "Upregulated expression of RIPK3 was observed in primary colorectal cancer and breast cancer and indicated poor prognosis." (PMID 35601830, 2022). "The antifungal drug miconazole was reported to induce both apoptotic and necroptotic cell death in human MDA-MB-231 breast cancer cells via augmented Bax/Bcl-2 ratio, upregulation of RIPK3 and MLKL phosphorylation levels, and ROS generation." (PMID 36361505, 2022). "TNFα/type I IFN enhancement of apoptotic priming in breast cancer recipient cells highlights a synergistic pro-death activity between these two inflammatory cytokines, recently reported to induce necroptosis in RIPK3 competent (non cancer) cells." (PMID 31937780, 2020). "To confirm that our observation is not a cell line-specific phenomenon, we also carried out soft agar growth assay by use of the mouse breast cancer 4T1 cells with the RipK3 gene knockout." (PMID 26959742, 2016). "RIPK3 serve as a crucial mediator in the necroptosis pathway, impacting liver cancer progression and chemotherapy-induced immunogenic cell death, with its expression levels correlating with immune infiltration in breast cancer tissues." (PMID 39349845, 2024). "As the activation of MLKL is associated with its phosphorylation by RIPK3, the effect of DS variants on the phospho-MLKL level in breast cancer cells might probably be mediated through the stimulatory impact of these glycans on the kinase activity." (PMID 39062543, 2024). "In addition, another study found that the knockdown of RIPK3 expression in recurrent breast cancer cells inhibited the proliferation of breast cancer cells and suppressed the activity of YAP/TAZ." (PMID 36675706, 2022). "Similarly, low RIPK3 expression indicates a worse prognosis in patients with breast cancer." (PMID 31122251, 2019). "Data from breast cancer research indicates that the formation of RIPK1/RIPK3 necrosomes is essential for mediating ICD in cancer cells, while autophagic degradation of necrosomes results in ICD failure in breast cancer cells." (PMID 41334873, 2025).
breast cancer (continued). "In human breast cancer, it has been shown that necrosis can occur through finely tuned regulation of a series of pro-necrotic genes including MLKL, RIPK1, RIPK3, PGAM5, and DFNA520." (PMID 38773214, 2024). "Recently, organoantimony (III) fluoride has also been shown to induce RIPK3-MLKL-dependent necroptosis through significant GSH depletion and ROS elevation in human MDA-MB-231 breast cancer cells." (PMID 36361505, 2022). "Except for the five genes ITPK1, RIPK3, STAT3, TNF, and FASLG, the remaining 62 genes showed significant differences in expression between breast cancer and normal breast samples." (PMID 36675706, 2022). "Zinc oxide nanoparticles (ZnO-NP) significantly induce necroptosis by the upregulation of RIPK1, RIPK3, and MLKL expression in human MCF-7 breast cancer cells." (PMID 36361505, 2022). "Knockout of the RIPK1, RIPK3, or MLKL genes in breast cancer cells significantly reduces the oncogenic activity of these cells and sensitizes the breast cancer cells to radiation therapy." (PMID 35965497, 2022). "RIPK1, RIPK3, and MLKL have been found to promote tumorigenesis in several breast cancer cell lines, and the suppression of these factors can significantly weaken the tumorigenicity and sensitize therapeutic response to radiotherapy." (PMID 33665167, 2020). "Our data also showed that ROS activated major necrosome complex cascade genes, such as RIPK, RIPK3, and MLKL, especially in YARS-overexpressing breast cancer cell lines." (PMID 33239070, 2020). "A clinical study of breast cancer tissue specimens showed that compared to adjacent non-cancerous tissues, the mRNA and protein expression levels of tumor necrosis factor alpha (TNFα), RIPK1, RIPK3, and MLKL were significantly elevated in breast cancer tissues." (PMID 41346619, 2025). "Since we observed that GPx1 deficiency enhanced TNF-α-induced apoptosis of MCF7 (luminal A type and RIPK3-negative) cells, the antiapoptotic function of GPx1 is thought to be independent of the molecular subtype of breast cancer." (PMID 34158609, 2021). "Here the authors show that ZBP1 is an upstream mediator of RIPK3 in tumour necroptosis and that glucose deprivation induces the release of mitochondrial DNA, which binds to ZBP1 to activate ZBP1-mediated necroptosis in breast cancer." (PMID 33976222, 2021). "Next, we treated YARS-overexpressing breast cancer cells with necroptosis inhibitors, including Nec-1 (inhibitor of RIPK), GSK’872 (inhibitor of RIPK3), and NSA (inhibitor of MLKL kinase), after SM/z-VAD.fmk treatment to confirm whether SM promotes necroptosis compared to apoptosis." (PMID 33239070, 2020).
colon carcinoma (33 papers, 2015 to 2025). "On the other hand, some studies reported conflicting observations, indicating increased levels of RIPK3 expression in human and mouse colonic cancers, including colitis-associated cancer (CAC)." (PMID 39540935, 2024). "Interestingly, RIPK1 and RIPK3 expression in colon cancer cells is reduced by hypoxia, a hallmark of solid tumor." (PMID 25675296, 2015). "Furthermore, RIPK3-deficiency leads to activation of the NF-κB pathway in colon cancer." (PMID 31766571, 2019). "By contrast, other studies have indicated a marked decrease in RIPK1 and RIPK3 expression in human colon cancer tissues compared to the adjacent normal tissues." (PMID 39540935, 2024). "In particular, the increased RIPK3 level by SPOP depletion sensitized LPS/sMAC/zVAD-induced necroptosis in HT-29 colon cancer cells." (PMID 39540935, 2024). "The deletion of SPOP, which led to increased stability of the RIPK3 protein, intensified LPS/sMAC/zVAD-induced necroptotic cell death in colon cancer cells." (PMID 39540935, 2024). "HT29, a colon cancer cell line that is widely used for RIPK3-necroptosis study, was used as a positive control." (PMID 36650126, 2023). "On the contrary, a study indicates that RIPK3, as a colon tumor suppressor, has an anti-tumoral function." (PMID 35884370, 2022). "2-methoxy-6-acetyl-7-methyljuglone (MAM) induces necroptosis in colon cancer cells by forming the RIPK1/RIPK3 complex, activating JNK and elevating ROS." (PMID 35884370, 2022). "For instance, mitochondria-derived ROS promoted autophosphorylation of RIPK1, which enabled RIPK1 to recruit RIPK3 to form necrosome (RIPK1/RIPK3), initiating TNFα-mediated necroptosis in colon cancer cells." (PMID 36211509, 2022). "Resibufogenine, a naturally occurring bioactive compound extracted from toad venom, has been shown to inhibit the growth and metastasis of colon cancer via triggering RIPK3/MLKL-dependent necroptosis in both in vitro and in vivo colon cancer models." (PMID 36361505, 2022). "The overexpression of RIPK3 combined with chloroquine (CQ) can solve multi-drug resistance colon cancer." (PMID 35884370, 2022). "RIPK3 expression has been found to positively relate to a better prognosis of colon cancer, which makes it a promising prognostic marker." (PMID 35884370, 2022). "Colon cancer cells overexpressing GLTP (HT-29) exhibit RIPK-3-mediated MLKL phosphorylation, increased intracellular Ca2+, levels and induce cell death through necroptosis." (PMID 36685937, 2022). "The same effect was observed in another cell line, human colon cancer HT-29 cells, which express endogenous RIPK3 and MLKL." (PMID 34862394, 2021). "Expression of genes involved in angiogenesis and mitogenic responsiveness, comprising the EGFR ligand Epiregulin (Ereg), matrix metalloproteinase 10 (Mmp10), and cyclooxygenase 2 (Cox2) were up-regulated in colon tumors of Ripk3−/− mice." (PMID 27344176, 2016). "We found that mRNA expression of Ripk1 and Ripk3 was significantly decreased in colon cancer tissues compared with paired normal colon tissues (P=0.0039 for Ripk1 and Ripk3 by Wilcoxon matched-pairs signed-rank test)." (PMID 25675296, 2015). "Similar increase in irinotecan-induced cell death was observed with another Smac mimetic BV6 and in another RIPK3-positive colon cancer cell line Colo205." (PMID 25675296, 2015). "To explore the role of necroptosis in chemotherapy-induced cell death, we used inhibitors of RIPK1 or RIPK3 kinase activity, and modulated their expression in colon cancer cell lines using short hairpin RNAs." (PMID 25675296, 2015). "In this study, we found that RIPK1 and RIPK3 expression was reduced in primary colon cancer tissues compared with normal adjacent tissues." (PMID 25675296, 2015). "Similarly impaired antitumor activity of combination ICI was also found in BALB/c mice bearing RIPK3−/− CT26 colon carcinoma tumors." (PMID 40345706, 2025).